IL1B (interleukin 1 beta)
Diseases named in the same sentence as IL1B in open-access papers (continued):
Sharing a sentence is not in itself a finding about the gene and the disease.
gastritis (58 papers, 2010 to 2025). Inflammation of the stomach. "Comparing to Il-1β (+ / +) mice, Il-1β (-/-) mice exhibited attenuated inflammatory cell recruitment, proliferation excess, and apoptotic deficiency to inhibit gastritis and carcinogenesis." (PMID 40264171, 2025). "On the other hand, studies in a specific Indian population showed that IL-1B-511*T carriers homozygous for the IL-1RN short allele (IL-1RN*2/*2) were more likely to develop gastritis after infection with Asian cagA strain of H.pylori." (PMID 38867324, 2024). "IL-1β, IL-6, and IL-8 were lower in H. pylori infection-associated gastritis samples, whereas the levels of IL-12, IL-18, and TNF-α were higher." (PMID 38561502, 2024). "The NLRP3 inflammasome activation and the IL-1β overexpression play crucial roles in the pathogenesis and development of Hp-associated gastritis." (PMID 36597090, 2023). "For further insight, an MCA was performed including the variables associated with the polymorphism cluster, which were the IL-1β levels in both the antrum and fundus and H. pylori density and gastritis activity scores, and was built accordingly." (PMID 36838318, 2023). "As reported, the activation of the NLRP3 inflammasome and production of large amounts of the pro-inflammatory factor IL-1β are crucial factors for the occurrence and progression of Hp-associated gastritis and gastric cancer." (PMID 36597090, 2023). "Europeans with IL-1B-511T/-31T/IL-1RN*2 have a high risk of GC, while in a Kazakh population, IL-1B-511T/T and IL-1B-31C/C increase the risk of gastritis." (PMID 35547123, 2022). "In this study, we further addressed Rabeprazole inhibited cell pyroptosis by destroying NLRP3 inflammasome, leading to decrease Caspase-1 activation and IL-1β and IL-18 release, and resulting in alleviating H. pylori-associated gastritis." (PMID 34266494, 2021). "The results of the study showed that seropositive gastric diseased patients with gastritis had higher rate 25% of IL-1B gene polymorphism at -511C/T site as compared to seronegative gastric diseased group with gastritis (8.3%)." (PMID 32494282, 2020). "There were some of the patients with gastritis showed polymorphism for this gene at both of these sites (IL-1B-511C/T plus -31T/C)." (PMID 32494282, 2020). "In this study, a significant association was observed between IL-1B+3954TT and T allele genotype and patients with gastritis and TT genotype and peptic ulcer compared with the control group." (PMID 30320011, 2018). "In this study, homozygous variant (TT) of IL-1B+3954 gene is associated with peptic ulcer and caring T allele (CT+TT) is correlated with gastritis." (PMID 30320011, 2018). "HSD causes severe gastritis, high gastric pH, increased parietal cell loss, increased gastric expression of IL-1β, and decreased gastric expression of hepcidin and hydrogen potassium ATPase (H,K-ATPase), compared to individuals on a regular diet." (PMID 26942879, 2016). "In the Japanese population, IL1B-511C > C polymorphism was dominant among patients with advanced atrophic chronic gastritis, whereas IL1B-511 T > T + T > C polymorphism was more frequent in the Chinese population." (PMID 24803922, 2014). "IL1A and IL1B genes have been proposed as key factors in determining risk of gastritis and malignant transformation." (PMID 23995914, 2013). "In the case of the Japanese population, IL1B–511C>C polymorphism was found dominant among patients with advanced atrophic chronic gastritis, whereas IL1B–511T>T+T>C polymorphism dominated among the Chinese population." (PMID 23995914, 2013). "IL-1B+3954 TT was associated with a high risk of gastritis and peptic ulcer [Odds Ratio (OR)]=2.63, 95% Confidence Interval (CI)= (1.47–4.70) (OR=3.40, CI=1.72–6.71) respectively and the IL-1B+3954 T allele was associated with chronic gastritis (OR=1.64, 95% CI=1.13–2.36)." (PMID 30320011, 2018).
gastritis (continued). "IL-1β, IL-18 have been shown to contribute to H. pylori induced gastritis, but the details of inflammation and association of virulence factors remain unclear." (PMID 27014647, 2015). "Since the presence of TT polymorphism in IL-1B has been reported as associated with increased gene expression and this increased expression enhances the severity of the gastric mucosal inflammatory responses, carriers of the TT genotype are susceptible to peptic ulcer and gastritis." (PMID 30320011, 2018). "In the early stage of H. pylori-induced gastritis or gastritis caused by other stimuli, immune cells such as macrophages and Th1 cells release large amounts of pro-inflammatory factors, including TNF-α, IL-1β, and IFN-γ." (PMID 41376630, 2025). "Consistent with our study, we proved that the infiltration of macrophages was substantially reduced and the expression level of the pro‐inflammatory mediator IL‐1β was downregulated in stress‐induced gastritis models treated with VE prevention and treatment." (PMID 40418631, 2025). "Key cytokines identified as playing a crucial role in the development and progression of gastritis include IL-1β, IL-6, IL-8, IL-12, IL-18, and TNF-α23–26." (PMID 38561502, 2024). "Generally, cytokine levels were higher in gastritis, but in H. pylori-infected gastritis, IL-1β, IL-6, and IL-8 levels were lower compared to H. pylori-independent gastritis, while IL-12, IL-18, and TNF-α levels were higher." (PMID 38561502, 2024). "The IL-1β’s varied expression in different gastritis contexts underscores its pivotal role in the inflammatory processes associated with this condition." (PMID 38561502, 2024). "Our investigation delves into the differential expression of key cytokines in gastric tissue, including IL-1β, IL-6, IL-8, IL-12, IL-18, and TNF-α in the context of H. pylori-associated and H. pylori-independent gastritis." (PMID 38561502, 2024). "In our experimental study, we observed that IL-1β levels were increased in gastritis compared to normal, yet interestingly, IL-1β levels in H. pylori-associated gastritis were lower than in H. pylori-independent gastritis." (PMID 38561502, 2024). "In our data, higher levels of IL-1β at the level of the antrum were exhibited in the early stages such as gastritis." (PMID 36838318, 2023). "As for VNTR, patients with different genotypes exhibited distinctive clinical/biological parameters (IL-1β levels, gastritis activity, H. pylori density score)." (PMID 36838318, 2023). "IL-1β is one of the best-studied mediators of Helicobacter-induced gastritis and upregulation of IL-1β is pronounced in H. pylori-infected patients who manifest high levels of IL-1β in their gastric mucosa." (PMID 37650975, 2023). "Children with Hp infection-related gastritis were considered to have relatively high IL-1β levels and relatively low 25-(OH) D3 levels due to chronic inflammatory reactions." (PMID 32968412, 2020). "Twenty-five percent of gastritis patients showed polymorphism for both (IL-1B-511 and IL-1B-31) genotypes whereas, only 8.3% of EFV patients showed polymorphism for IL-1B-31T/C." (PMID 32494282, 2020). "The genotype frequencies of the IL-1B +3954 TC and TT were significantly different between gastritis and control group (OR=1.40, CI=0.94–2.09, and OR=2.63, CI=1.47–4.70) respectively." (PMID 30320011, 2018). "As a result, macrophage-related inflammatory mediators, including IL-1β, VEGF, IL-6, and MMP-2, all known to be engaged in either H. pylori-associated gastritis or carcinogenesis, were significantly increased in Group II." (PMID 26317548, 2015). "H. pylori gastritis and its role in mucosal activation of innate immunity and upregulation of IL-1β is also suggested in the pathogenesis of IR." (PMID 25202440, 2014). "In the present study, mRNA levels of the pro-inflammatory cytokine IL-1β were up-regulated in the antrum of gerbils suffering from gastritis." (PMID 23895283, 2013).
gastritis (continued). "IL-1β was also up-regulated in the stomach of our gerbils with gastritis and in the present study, gastrin mRNA was up-regulated in the fundus of gerbils inoculated with strains ASB2 and ASB6." (PMID 23895283, 2013). "Artemisia capillaris Thunb. from Asteraceae revealed remarkable early-stage anti-gastritis ability and anti-chronic gastritis and anti-precancerous lesion capacity by down-regulating IL-1β, IL-6, TNF-α, COX-2, PGE2, gastric F4/80 protein, and MDA with low p-p65 and pSTAT3 expression." (PMID 40264171, 2025). "Interleukin 1β (IL-1β) plays a key role in the inflammatory pathway - when induced by H.pylori infection, it inhibits gastric acid secretion, which promotes H.pylori colonization and leads to more severe gastritis." (PMID 38867324, 2024). "Moreover, its involvement in the pathogenesis of peptic ulcers, irrespective of H. pylori infection, aligns with our observations, suggesting a complex relationship between IL-1β levels and H. pylori status in gastritis." (PMID 38561502, 2024). "EPS54 also significantly alleviated the symptoms of gastritis in the H. pylori-infected mice by down-regulating the mRNA expression levels of pro-inflammatory cytokines IL-6, IL-8, IL-1β and TNF-α and up-regulating the mRNA expression of inflammatory cytokines IL-10 in gastric cells." (PMID 38978704, 2024). "Most importantly, VNTR genotypes might stratify patients through their clinical/biological parameters such as IL-1β levels, gastritis activity and H. pylori density scores." (PMID 36838318, 2023). "Interestingly, EtOH/HCl-induced gastritis mouse models demonstrated an increase in IL-1β, iNOS, TNF-α, INF-β, and COX-2 gene expression and an increase in phosphorylation of p65, Syk, and JAK2." (PMID 31929819, 2019). "The genes IL1B and IL8 are suggested as key factors in determining the risk of gastritis." (PMID 24803922, 2014). "EPS54 could also effectively alleviate the gastritis in the H. pylori-infected mice by down-regulating the mRNA expression levels of pro-inflammatory cytokines IL-6, IL-8, IL-1β and TNF-α and up-regulating the mRNA expression of inflammatory cytokine IL-10 in gastric cells." (PMID 38978704, 2024). "Moreover, it was found that silencing of AQP5 could restrain levels of inflammatory factor (TNF-α and IL-1β) and apoptosis of GECs in mice with H. pylori-related gastritis." (PMID 35538066, 2022). "However, Tnfα and Il-1β expressions were significantly higher in the 2S group than those in the HP group, suggesting that a high concentration of solar salt may aggravate gastritis." (PMID 36430475, 2022). "Indeed, chronic inflammation plays a major role, and proinflammatory cytokines appear to promote progression from gastritis to cancer; in particular, the interleukin (IL)-1 family members, such as IL-1β and IL-18, have been shown to induce gastric carcinogenesis in animal models." (PMID 34071419, 2021). "Therefore, IL-1β is an important signaling mediator in the promotion of gastritis." (PMID 30382864, 2018). "IL-1B polymorphisms were not statistically associated with the prediction of each diagnose as according, however p-value to determine association between polymorphism and outcome of infection (diagnose severity: gastritis or cancer) was 0.084." (PMID 26401131, 2015). "Neutral corn protein hydrolysate attenuated gastritis through reduction of MPO, IL-1β, IL-6, KC, TNF-α, and MCP-1." (PMID 40264171, 2025). "Our study provides invaluable insights into the inflammatory mechanisms involved by exploring key cytokines such as IL-1β, IL-6, IL-8, IL-12, IL-18, and TNF-α in gastritis." (PMID 38561502, 2024). "Commercially available ELISA plates were used to confirm further the influence of H. pylori infection on the expression of cytokines (IL-1β, IL-6, IL-8, IL-12, IL-18, and TNF-α) in gastritis." (PMID 38561502, 2024).
gastritis (continued). "We also confirmed that Mh-ME mitigates acute gastritis derived from HCl/EtOH in ICR mice, ameliorating the expression of IL-1β and tumor necrosis factor-alpha (TNF-α)." (PMID 37687291, 2023). "The *1/*1 genotype was closely situated to the cluster of patients with moderate and severe gastritis activity scores (PNN2 and PNN3, respectively), severe H. pylori density scores (HP3) and low levels of IL-1β expression in the antrum and fundus." (PMID 36838318, 2023). "It was found that treatment with gentiopicrin significantly improved alcohol-induced gastritis in mice, mainly by decreasing the production of pro-inflammatory cytokines TNF-α, IL-1β, and IL-8, and increasing the level of anti-inflammatory cytokine IL-10." (PMID 37765116, 2023). "Even in in vivo models of Helicobacter pylori-induced gastritis in Mongolian gerbils, CAPE can prevent NF-κβ activation and decrease COX-2, iNOS, IL-1β, and TNF-α mRNA expression." (PMID 36673507, 2023). "The *1/*4 genotype was clustered with patients presenting low gastritis activity scores (PNN1) and both low and moderate H. pylori density scores (HP1 and HP2, respectively) with higher levels of IL-1β in the antrum and the fundus." (PMID 36838318, 2023). "In the mouse gastritis model, Gc-ME administration ameliorated stomach ulcers and reduced the expression of inflammatory genes (COX-2, IL-1β, IL6, and iNOS) and the phosphorylation of Src and IκBα." (PMID 36559672, 2022). "The results of the in vivo mouse acute gastritis model showed that ICE significantly reduced inflammatory lesions in the gastric mucosa and remarkably downregulated the expression of iNOS, TNF-α, IL-1β, and IL-6 mRNA in gastric tissue." (PMID 36386225, 2022). "The study results showed that TNF-α, IL-1β, IL-6, TLR4, and MBL2 are common among Covid-19, IBD, gastritis, and diarrhea." (PMID 35845309, 2022). "Our results indicate that heparanase promotes M1 polarization of macrophages driven by H. pylori or LPS + INF-γ, resulting in increased expression of pro-inflammatory cytokines such as IL-1β, IL-6 and TNF-α, and further aggravating the severity of gastritis." (PMID 34220822, 2021). "The IL-1β, IL-6, and IL-8 levels were lower in H. pylori-infected gastritis compared to non-infected gastritis." (PMID 38561502, 2024). "In H. pylori infection-associated gastritis, the IL-1β, IL-6, and IL-8 were lower, whereas IL-12, IL-18, and TNF-α were higher than those in gastritis without H. pylori infection." (PMID 38561502, 2024). "Furthermore, individuals with Hp gastritis at high altitudes demonstrate elevated levels of serum TNF-α, IL-1β, IL-6, and MDA, as well as reduced serum SOD and GSH-Px activities." (PMID 38970131, 2024). "At this level, patients with H. pylori-induced gastritis exhibiting no advanced stage showed higher levels of IL-1β when compared to non-infected patients." (PMID 36838318, 2023). "Additionally, PDG derived from a marine sponge-associated actinomycete decreased the levels and expression of various inflammatory markers, including myeloperoxidase, IL-1β, TNF-α, iNOS, Cox-2, and NF-κB in a murine gastritis model." (PMID 35336729, 2022). "FRVE significantly reduced H. pylori‐induced gastritis, although such effect was not due to altered IL‐1β or TNF‐α expression in mice." (PMID 33598173, 2021). "In addition, similar to phenotype of Cc-ME in gastritis model, increased mRNA levels of inflammatory genes (COX-2, IFN-β, IFN-γ, IL-1β, IL-6, iNOS, and TNF-α) were also significantly suppressed in both Cc-ME- and ranitidine-treated groups." (PMID 29725354, 2018). "In addition, FRVE significantly reduced H. pylori‐induced gastritis, although such effect was not due to altered IL‐1β or TNF‐α expression in mice." (PMID 33598173, 2021).
gastritis (continued). "Likewise, *1/*1 genotype carriers clustered with severe gastritis activity and H. pylori density scores along with low levels of IL-1β in the antrum and fundus, while the *1/*2 genotype was clustered with non-infected-patient features and normal IL-1β levels." (PMID 36838318, 2023). "Focusing on Il-1β, IL-6, IL-8, IL-12, IL-18, and TNF-α, we analysed gene and protein levels to differentiate between H. pylori-infected and non-infected gastritis." (PMID 38561502, 2024). "Moreover, other inflammatory cytokines and chemokines (IL-27, IFN-β, IL-1α, IL-23, IL-22P70, TNF-α, IL-17A, IL-10, IL-1β, and MCP-1) were not showed dose-dependent changed in DFMO-treated mice compared to gastritis mice group." (PMID 32231118, 2020).
hepatitis (58 papers, 2008 to 2026). Inflammation of the liver. "In hepatitis A, B, and C, there are elevated levels of IL-1β, thus indicating a potential role for the inflammasome." (PMID 33203036, 2020).